GNLY (granulysin)
Diseases named in the same sentence as GNLY in open-access papers (continued):
Sharing a sentence is not in itself a finding about the gene and the disease.
Sepsis (6 papers, 2022 to 2025). Sepsis is defined as life-threatening organ dysfunction caused by a dysregulated host response to infection. "Zhang Q found that the hub genes GNLY may be associated with the prognosis of sepsis." (PMID 36199375, 2022). "Survival analysis screened four genes positively correlated with sepsis prognosis, namely GNLY, GZMB, PRF1 and RASGRP1." (PMID 38057716, 2023). "In addition, these results are strengthened by a significantly lower cytotoxic module score (calculated using the AddModuleScore function in Seurat V4 using the cytotoxic-related genes GZMH, GZMK, GZMA, GZMB, PRF1, and GNLY) in all sepsis cytotoxic cell subsets compared to bacteraemia and controls." (PMID 41208955, 2025). "GNLY, GZMB, PRF1, and RASGRP1, which are lysosome-related genes, are closely linked to the prognosis of sepsis and could potentially serve as novel research targets for sepsis, offering valuable insights for the development of lysosome-targeted therapy." (PMID 38057716, 2023). "Furthermore, the hub genes TLR5, FCGR1A, ELANE, GNLY, IL2RB and TGFBR3, which may be associated with the prognosis of sepsis, and their negatively correlated microRNAs, were analysed." (PMID 35332254, 2022). "In conclusion, the genes GNLY, GZMB, PRF1, and RASGRP1 exhibited significant upregulation in the normal control group and downregulation in the sepsis group, thereby displaying a positive correlation with the prognosis of sepsis patients." (PMID 38057716, 2023). "The analysis revealed that GNLY, GZMB, PRF1, and RASGRP1 exhibited high expression levels in the normal control group, while their expression was low in the sepsis group." (PMID 38057716, 2023). "In the two groups of different expression trend modules, the core genes such as CD160, GATA2, GNLY, IL2RB and TGFBR3 were downregulated in the sepsis group, while genes such as ELANE, IL1R1, TLR5, FCGR1A, MAPK14 and PCSK9 were upregulated." (PMID 35332254, 2022). "However, downregulated genes in sepsis NK cells similarly included cytotoxicity-related genes (GZMH, GNLY & GZMB, -1.42log2FC, -1.29log2FC & -0.48log2FC, respectively)." (PMID 41208955, 2025). "TBX21, GNLY, PRF1, and IL2RB represent the immune status in sepsis." (PMID 41139765, 2025). "S1PR5, GNLY, CD247, KLRG1, IL-1R2, AUTS2, IL-2Rβ, ARG1, TGFBR3, TLR5 and PRF1 in the top 80 genes in the two modules were located toward the center of the co-expression network, and CD247, IL-2Rβ, TGF-βR3 and IL-1R2 were identified as core genes in sepsis." (PMID 36855106, 2023). "Notably, the analysis revealed that GNLY, GZMB, PRF1, and RASGRP1 exhibited significantly higher expression levels in the normal control group compared to the sepsis group (P<0.05)." (PMID 38057716, 2023). "GNLY, GZMB, PRF1, and RASGRP1 are lysosome-related genes that are closely related to the prognosis of sepsis, and may be used as new research targets for sepsis and provide direction for lysosome-targeted therapy." (PMID 38057716, 2023). "Consequently, the genes TLR5, FCGR1A, ELANE, GNLY, IL2RB and TGFBR3 genes were ultimately identified as hub genes in sepsis." (PMID 35332254, 2022). "Furthermore, the widespread downregulation of specific cytotoxic and cytolytic genes, including GNLY, GZMH and NKG7, across CD8+ T cells, NK cells, CD56+ T cells, MAIT cells and γδ T cells reported here was found to negatively impact survival outcomes in sepsis." (PMID 41208955, 2025).
graft versus host disease (5 papers, 2014 to 2021). An immune system disorder that occurs after allogeneic hematopoietic stem cell transplant and is a reaction of donor immune cells against host tissues. "GNLY is a specific protein that, besides cytotoxic activity, serves as a distinctive biomarker of cell-mediated immunity, tumor immunity, infection, and graft versus host disease (GVHD)." (PMID 34681139, 2021). "Granulysin, a cationic protein expressed by human natural killer cells and cytotoxic T lymphocytes, is a mediator for drug-induced Stevens-Johnson syndrome and graft-versus-host disease." (PMID 27276051, 2016). "Furthermore, serum levels of granulysin are markedly heightened and correlated with the severity of graft vs. host disease (GVHD), which may mimic SJS and TEN when it presents as similar dermatological manifestations in bone marrow transplant recipients." (PMID 24394640, 2014). "Besides cytotoxic activity, GNLY serves as a distinguishing biomarker of cell-mediated immunity, infection, and graft versus host disease (GVHD)." (PMID 34945761, 2021).
toxic epidermal necrolysis (5 papers, 2016 to 2024). Toxic epidermal necrolysis (TEN) is an acute and severe skin disease with clinical and histological features characterized by the destruction and detachment of the skin epithelium and mucous membranes. "Recently, it has also been shown that, besides in toxic epidermal necrolysis (TEN), granulysin is also expressed by CD4 and CD8 T cells and natural killer (NK) cells in different drug reactions including AGEP, suggesting that granulysin may also play a role in the pathogenesis of AGEP." (PMID 27472323, 2016).
autoimmune disease (4 papers, 2021 to 2025). A disorder resulting from loss of function or tissue destruction of an organ or multiple organs, arising from humoral or cellular immune responses of the individual to their own tissue constituents. "Elevated expression of GNLY in tissue and serum has been associated with infections, autoimmune disease, transplant rejection, and graft-versus-host reactions." (PMID 39851522, 2025).
leprosy (4 papers, 2011 to 2025). Leprosy is a chronic infectious disease affecting primarily the skin and peripheral nervous system. "Analogously, granulysin-expressing T cells were more frequently found in tuberculoid (localized) leprosy lesions than in lepromatous (disseminated) leprosy lesions." (PMID 36409085, 2022). "Together, the results indicate that LipoK could contribute to protective host response against leprosy and eventually kill the bacteria, through the production of perforin, granulysin and granzyme B in T cells." (PMID 22132248, 2011). "Reports have shown the ability of T cells to secrete granulysin at the site of M. leprae infection, which provides evidence that anti-microbial activity of granule containing T cells is a mechanism of host defense in leprosy." (PMID 22132248, 2011). "But, this fact was in lines with the earlier data, which showed co-localization of granulysin and CD4+ T cells in tuberculoid leprosy lesions." (PMID 22132248, 2011).
myeloma (4 papers, 2018 to 2022). "None of the investigated non-Hodgkin B cell lymphomas, Hodgkin lymphoma and plasma cell myeloma were granulysin positive." (PMID 30151671, 2018). "Recently, we demonstrated the great efficacy of recombinant granulysin in two in vivo tumor development models in nude mice, mammary carcinoma MDA-MB-231 and multiple myeloma NCI-H929." (PMID 32859066, 2020).
pulmonary TB (4 papers, 2014 to 2023). "Previous investigations have demonstrated that 1,25(OH)2D3 downregulates the cytotoxic effector response in pulmonary tuberculosis by reducing the expression of perforin, granulysin, and granzyme B." (PMID 35563767, 2022). "Moreover, effector perforin- and granulysin-expressing CD8+ T cells were detected in tuberculous granulomas in patients with pulmonary tuberculosis." (PMID 37761328, 2023).
Crohn disease (3 papers, 2007 to 2022). A gastrointestinal disorder characterized by chronic inflammation involving all layers of the intestinal wall, noncaseating granulomas affecting the intestinal wall and regional lymph nodes, and transmural fibrosis. "Employing scRNA sequencing here the authors identify CD127+ CD94+ innate lymphoid cells that express granulysin and perforin and are expanded in patients with Crohn’s disease." (PMID 34615883, 2021). "Similarly, CD127+CD94+ ILCs identified in human lamina propria were reported to secrete granulysin in response to IL-15 and to accumulate in Crohn’s disease patients." (PMID 35300331, 2022). "Thus, granulysin producing CD127+CD94+CD117−ILCs accumulated in inflamed resection specimen from Crohn’s disease patients, but not at the cost of conventional helper ILCs." (PMID 34615883, 2021).
endometriosis (3 papers, 2021). The growth of functional endometrial tissue in anatomic sites outside the uterine body. "FLT1 and SCN11A were up-regulated and GNLY was down-regulated, suggesting that endometriosis is associated with an inflammatory response." (PMID 33868805, 2021). "Regarding the mechanisms of low PBMC cytotoxicity in patients with endometriosis, the toxic granules (granzyme B, perforin, and granulysin) and surface receptors (NKG2D, NKp30, NKp46, CD158a, and CD158b) of peripheral NK cells were analyzed." (PMID 34531861, 2021). "The highly differential genes between the two groups showed that C–C motif chemokine ligand 3 (CCL3) and X-C motif chemokine ligand 1 (XCL1) were significantly elevated in endometriosis while cytotoxic molecules including GNLY, GZMB and GZMH were significantly down-regulated." (PMID 34039410, 2021).
Granuloma (3 papers, 2016 to 2022). A compact, organized collection of mature mononuclear phagocytes, which may be but is not necessarily accompanied by accessory features such as necrosis. "This condition may differ from that of chronic TB, which is characterized by persistent inflammation and active clinical manifestations, and is associated with diminished GNLY in granuloma-associated CTLs, resulting in impaired CTL activities." (PMID 27756230, 2016). "Perforin and granulysin appeared to be depleted from CD8 cells in TB lung granulomas compared with uninfected control, raising the possibility that active TB granulomas develop when there is insufficient granulysin and perforin expression in diseased tissue." (PMID 36409085, 2022). "Although CD8+ T cells expressing granulysin and perforin were scarce in granuloma lesions in TB, however, perforin is critical for host immune defense during Mtb infection, even though the cytolytic activity in vivo is slightly affected in the absence of perforin." (PMID 32823923, 2020).
neuroblastoma (3 papers, 2023 to 2024). Neuroblastoma (NB) is the most common solid, extracranial childhood tumor. "expanded NK cells and isolated NK‐Exos loaded with cytotoxic proteins, including perforin, granzyme A, granzyme B, granulysin and FasL, and found that NK‐Exos triggered cytochrome C release from mitochondria and ER stress in recipient neuroblastoma (NB) cells." (PMID 37830387, 2023). "In neuroblastoma, it was revealed that proteins within NK-cell-derived sEVs, such as perforin, granzyme A, granzyme B, and granulysin functioned in combination to induce cytotoxicity to CHLA255, a neuroblastoma cell line." (PMID 37762393, 2023).
parasitemia (3 papers, 2020 to 2022). "CD8-depleted GNLY-Tg mice exhibited higher parasitemia 8 DPI in comparison to control groups (treated with αKLH or untreated)." (PMID 32913355, 2020). "Granulysin is an anti-microbial and anti-tumorigenic molecule which is expressed in response to viral, bacterial, fungal, and parasitic infections and against tumor cells." (PMID 32054883, 2020). "Importantly, our results show that GNLY-transgenic mice more efficiently control parasitemia and that depletion of CD8+ T cells ablates the protective effect of GNLY." (PMID 32913355, 2020). "Finally, we evaluated the importance of CD8+ T cells and GNLY in host resistance to P. yoelii infection by comparing survival and parasitemia in WT, β2-m KO and GNLY-Tg mice." (PMID 32913355, 2020). "The Lieberman lab finds that GNLY-Tg mice have greater survival and decreased parasitemia compared to non-Tg mice after infection with T. cruzi and T. gondii." (PMID 36409085, 2022).
preeclampsia (3 papers, 2012 to 2022). Preeclampsia is a hypertensive disorder of pregnancy that is characterized by new-onset hypertension with proteinuria presenting after 20 weeks of gestation, and depending on mild or severe forms may initially present with severe headache, visual disturbances, and hyperreflexia. "Granulysin was previously associated with the development of preeclampsia as a Th1 marker." (PMID 21912564, 2012).
viral infection (3 papers, 2020 to 2024). "In addition, granulysin with diverse activities of NK cells and CTL in physiological and pathological settings in viral infection could be a useful novel serum marker to evaluate the overall status of host cellular immunity." (PMID 32823923, 2020).
vitiligo (3 papers, 2021 to 2024). Generalized well circumscribed patches of leukoderma that are generally distributed over symmetric body locations and is due to autoimmune destruction of melanocytes. "The aim of this study was to investigate the possible role of serum granulysin and cathepsin-L in the etiopathogenesis of vitiligo and their association with disease activity and severity." (PMID 38775500, 2024). "There are a very limited number of recent studies on the possible role of granulysin and cathepsin-L in the etiopathogenesis of vitiligo and as indicators of disease severity and activity." (PMID 38775500, 2024). "This is in contrast to the CD56+ NK cells, where fewer cells were GNLY+ and which predominated in halo nevus lesions compared to vitiligo." (PMID 39020008, 2024). "In this study, we demonstrated for the first time an increased expression of CD8+ GNLY+ T lymphocytes and CD56+ GNLY+ NK cells in lesions of vitiligo and halo nevus, indicating the role of GNLY in the pathogenesis of both diseases." (PMID 39020008, 2024). "A very high positive correlation was found between serum granulysin and cathepsin-L levels in vitiligo patients." (PMID 38775500, 2024). "In this study, we investigated the expression patterns of the cytolytic molecule granulysin (GNLY) in different cytotoxic cells in skin samples of vitiligo and halo nevus." (PMID 39020008, 2024). "The expression of GNLY+ cells was significantly higher in lesional skin of vitiligo and halo nevus compared to healthy skin, with significantly higher expression in halo nevus compared to vitiligo lesions." (PMID 39020008, 2024). "It is noteworthy that almost all CD8+ cells in vitiligo lesions and to a lesser extent in halo nevus lesions expressed GNLY+." (PMID 39020008, 2024). "The mean serum levels of granulysin and cathepsin-L were statistically significantly higher in vitiligo patients compared with the control group (p=0.048 and p=0.024, respectively)." (PMID 38775500, 2024). "There was a slight but non-significant positive correlation between the expression of GNLY in the epidermis and dermis of vitiligo lesions and the VES or VIDA score." (PMID 39020008, 2024). "GNLY+ cells are significantly more abundant in the perilesional skin of vitiligo and halo nevus compared to HC." (PMID 39020008, 2024). "There was a statistically significant positive correlation between epidermal and dermal granulysin in the lesional skin of vitiligo." (PMID 39020008, 2024). "GNLY+ cells were mainly accumulated in the dermal compartments of vitiligo lesions and less in the basal and suprabasal compartments of the epidermis." (PMID 39020008, 2024). "CD56+ GNLY+ NK cells were mainly identified in the dermal infiltrates of the perilesional skin of vitiligo, where they were significantly more abundant than in halo nevus or healthy skin." (PMID 39020008, 2024). "Remarkably, significantly more GNLY+ cells were present in the perilesional skin of vitiligo than in halo nevus." (PMID 39020008, 2024). "A significantly higher accumulation of GNLY+, CD8+ GNLY+ and fewer CD56+ GNLY+ cells was found in the lesional skin of vitiligo and halo nevus than in the healthy skin." (PMID 39020008, 2024). "CD56+ GNLY+ NK cells were found in dermal infiltrates in vitiligo and in the vicinity of nevus cells." (PMID 39020008, 2024). "Similar to lesional skin in vitiligo, distribution analysis showed that GNLY+ cells were mainly found in dermal infiltrates and in the basal layer of the epidermis." (PMID 39020008, 2024). "In addition, data on the relationship between serum GNLY and the activity as well as severity of vitiligo are contradictory." (PMID 39020008, 2024). "The results lack a functional characterisation of GNLY molecule in vitiligo and halo nevus." (PMID 39020008, 2024).
vitiligo (continued). "As expected, GNLY+ cells accumulated more frequently in lesional than perilesional skin in both diseases, but the frequency of GNLY+ cells was twice as high in halo nevus lesions as in vitiligo lesions, suggesting a stronger cytotoxic response in halo nevus lesions." (PMID 39020008, 2024). "CD56+ GNLY+ NK cells were also upregulated in lesions of vitiligo and halo nevus, although, they predominated in the lesions of halo nevus compared to vitiligo." (PMID 39020008, 2024). "However, there are no data in the literature on the expression of the cytolytic molecule GNLY in the lesional and perilesional skin of vitiligo and halo nevus." (PMID 39020008, 2024). "Therefore, further studies are needed to clarify whether granulysin acts as a cytotoxic or as an immune alarmin molecule in the pathogenesis of vitiligo and halo nevus." (PMID 39020008, 2024). "In vitiligo, most CD8+ GNLY+ cells were located in the perilesional dermis near melanocytes, whereas they were completely absent in healthy skin." (PMID 39020008, 2024). "This study investigates whether granulysin and cathepsin-l could be indicators of cell-mediated cytotoxicity in the pathogenesis of vitiligo and whether their levels measured in the acute phase could be markers that can help predict disease activity and prognosis of vitiligo." (PMID 38775500, 2024). "Similar to lesional skin, CD56+ GNLY+ NK cells were also significantly upregulated in the perilesional skin of vitiligo, although not in the perilesional skin of halo nevus." (PMID 39020008, 2024). "Similarly, but to a lesser extent, upregulation of GNLY+ and CD8+ GNLY+ cells was observed in the perilesional skin of vitiligo and halo nevus compared to healthy controls." (PMID 39020008, 2024). "In this study, we have shown that both CD8+ T lymphocytes and CD56+ NK cells expressing GNLY are abundant in the lesional skin of vitiligo and halo nevus, but not in healthy skin." (PMID 39020008, 2024). "There was also a positive correlation between epidermal and dermal GNLY in the perilesional skin of vitiligo, although not significant." (PMID 39020008, 2024). "In the lesions of vitiligo and halo nevus, fewer CD56+ NK cells expressing GNLY were found than CD8+ T lymphocytes expressing GNLY, which may indicate that CD8+ GNLY+ might play a dominant role in both diseases." (PMID 39020008, 2024). "The majority of CD8+ GNLY+ cells were located in the dermis and to a lesser extent in the basal epidermis of vitiligo, whereas they were completely absent in healthy skin." (PMID 39020008, 2024). "Although granulysin and cathepsin-L are molecules involved in the pathogenesis of vitiligo, the use of these molecules may not be helpful in assessing disease activity and severity." (PMID 38775500, 2024). "However, data on the role of GNLY-mediated cytotoxicity in the development of vitiligo and halo nevi are currently lacking." (PMID 39020008, 2024). "Therefore, it would be important to clarify the role of GNLY in the development of vitiligo and halo nevus, which has not been investigated so far." (PMID 39020008, 2024). "Although granulysin and cathepsin-L are molecules that play a role in the etiopathogenesis of vitiligo, they may not be useful for the assessment of disease severity and activity." (PMID 38775500, 2024). "The GNLY+ expressing NK cells were found just beneath the epidermis, near the melanocytes/nevus cells in the lesional skin of vitiligo and halo nevus as well as in the perilesional skin of vitiligo, while there were no such cells in the perilesional skin of halo nevi." (PMID 39020008, 2024).